LIN28B (lin-28 RNA binding posttranscriptional regulator B)
Diseases named in the same sentence as LIN28B in open-access papers (continued):
Sharing a sentence is not in itself a finding about the gene and the disease.
tumor (continued). "To determine if tumor-derived exosomes can induce pre-metastatic niches, we intravenously injected 4TO7 tumor-derived exosomes into naïve mice and the results showed that in vivo administration of Lin28B-exosome induced higher expression of niche characteristic genes in the lung." (PMID 35173168, 2022). "However, the normal function of LIN28B in the development of sympathetic neurons and chromaffin cells, the timing and the mechanisms involved in LIN28B-induced tumor formation are not completely known." (PMID 34771690, 2021). "Therefore, LIN28B-induced NB formation seems to require cooperation with additional signals activated in tumor founder cells at late postnatal stages." (PMID 34771690, 2021). "Intriguingly, histopathological examination revealed that CDX2 knockdown in the context of LIN28B overexpression dramatically converted the tumor’s differentiation status from well or moderately differentiated, which have gland-like structures, to poorly differentiated." (PMID 33755595, 2021). "Moreover, LIN28B contributes to metastases formation by increasing the invasive and migratory ability of tumor cells and, thus, confers the aggressive phenotype HR-NB tumors." (PMID 34072462, 2021). "In this review, we have focused on the circuitry linking the oncogenic transcription factors MYCN and PHOX2B with their transcriptional targets ALK and LIN28B and the tumor suppressor microRNAs let-7, miR-34 and miR-204, which should act as down-regulators of their expression." (PMID 34771690, 2021). "Therefore, we next focused on how CDX2 can modulate the CRC tumor progression in the context of LIN28B overexpression." (PMID 33755595, 2021). "Thus, this study provides an insight of molecular mechanism of LIN28B/ STAT3 into the tumor-initiation capacity of CCA." (PMID 34837926, 2021). "LIN28B is best known to negatively regulate the biogenesis of tumor-suppressive microRNAs, let-7." (PMID 32651364, 2020). "In conclusion, our results indicated that, beyond the direct inhibition of protein-coding tumor suppressors, miR-21 indirectly promotes the expression of pro-oncogenic factors like LIN28B by downregulating miRNAs of the let-7 family expression via mechanisms yet to be characterized in detail." (PMID 34316687, 2020). "Notably, it was only overexpression of LIN28B driven by this promoter that previously resulted in tumor formation." (PMID 30635573, 2019). "Notably, downregulation of RPSAP52 impairs the balance between the oncogene LIN28B and the tumor suppressor let-7 family of miRNAs, inhibits cellular proliferation and migration in vitro and slows down tumor growth in vivo." (PMID 31484926, 2019). "Interestingly, two tumor suppressor miRs, miR-26a-5p and miR-26b-5p, which directly regulate LIN28B, are in turn affected by N-MYC expression, leading to N-MYC-driven LIN28B-mediated oncogenic processes." (PMID 31867575, 2019). "LIN28B protein was shown to be an independent risk factor determining a poor outcome in NB, through negative regulation of let-7 miRNA, that leads to a high MYCN protein expression and, therefore, to an aggressive tumor phenotype." (PMID 31575060, 2019). "However, the tumor development in this mouse model is induced by Lin28B-mediated downregulation of Let-7 resulting in overexpression of MycN protein." (PMID 30760980, 2019). "Thus, our data reveal that the tumor-suppressive functions of Ezh2 are to maintain repression of a small number of oncogenes, including Plag1 and potentially Lin28b, which, upon derepression, contribute to more rapid AML development." (PMID 30890554, 2019). "Finally, to functionally validate the in vivo effects of LIN28B on tumor cell apoptosis, we subcutaneously transplanted A2780 cells (LIN28B knockdown) and TOV-112D cells (LIN28B overexpression) into nude mice." (PMID 30174831, 2018). "UFC1 acted as a ceRNA for Lin28b oncogene by sponging tumor-suppressive miR-498." (PMID 29970131, 2018).
tumor (continued). "LIN28B expression of mice tumor tissues was detected by Western blot and immunofluorescence assay." (PMID 30154460, 2018). "Furthermore, the regulation of LIN28B on BIM protein expression was validated by immunohistochemistry staining of xenograft tumor sections generated from A2780 (LIN28B shRNA) cells and TOV-112D (LIN28B overexpression) cells." (PMID 30174831, 2018). "There was a negative association between the expression level of Lin28b and that of miR-498 in tumor tissues (r = − 0.414, P < 0.01)." (PMID 29970131, 2018). "More importantly, restoration of LIN28B expression with a miR-203-resistant LIN28B overexpression plasmid completely reversed the miR-203-induced cellular phenotypes, suggesting that targeting LIN28B is a major mechanism by which miR-203 exerts its tumor-suppressive functions." (PMID 28218277, 2017). "Notably, ectopic expression of LIN28B increased tumorigenicity, while silencing LIN28B led to slow tumor growth in vivo." (PMID 28693523, 2017). "Thus, the authors proceeded to the detection of Lin28B transcript by RT-PCR and found its expression in 33.3% of HCC cases, with a significant association with larger tumor size, higher tumor grade and earlier recurrence after hepatectomy." (PMID 27738343, 2017). "Both Lin28B and Lin28A specifically interact with the loop sequence of pre-let-7, an interaction that modulates oligo-uridylation and degradation of pre-let-7; the maturation process leads to the well-known post-transcriptional tumor suppressor, let-7." (PMID 27821801, 2016). "Next, we investigated whether Lin28B knockdown can rescue the cell proliferation and the tumor sphere formation." (PMID 26028027, 2016). "Indirect evidence is provided by the vav-Lin28b model in which expression of Lin28b led to a pro-inflammatory environment whereby tumour cells expressed NFkB and tumours contained many pro-inflammatory cytokines and the association of ALCL with insect bites and breast implants." (PMID 27683157, 2016). "A number of fast evolving, placental genes show tumorigenic or tumor suppression activity (ADAM12, ADAMTS18, CAPN6, EGFL6, HTRA4, LIN28B) and others are involved in disorders associated with epithelial and connective tissues (FBN2) or have immune functions (IL1RL1, PRG2, SIGLEC6)." (PMID 26641094, 2015). "Moreover, conditional LIN28B deletion or siRNA-mediated LIN28B knockdown reduced tumor burden, inhibited metastasis and prolonged survival in vivo." (PMID 26478718, 2015). "Lin28B was overexpressed in some of the tumors from breast (1/5), uterus (1/5), lung (4/5), liver (1/5), and ovary (1/5), but was expressed at very low levels in the non-tumor tissue." (PMID 24244607, 2013). "Therefore, we compared expressions of Lin28A and Lin28B in primary OSCCs and analysed their clinical significances, respectively and collectively, in correlation with tumour clinical features and patient clinical outcomes." (PMID 24386298, 2013). "Over-expression of Lin28B (> 100×) was observed in 8 tumor tissue samples (53.3%)." (PMID 24244607, 2013). "The expression of Lin28B in circulating cells was significantly associated with non-cirrhotic liver (P=0.021), high tumor grade (P=0.046), large tumor size (P=0.005), high AJCC stage (P=0.044) and BCLC stage (P=0.017)." (PMID 24244607, 2013). "The findings may explain the effect of Lin28B on cell proliferation, epithelial to mesenchymal transition, invasion and tumorigenesis in vitro, as well as the high tumor grading and early tumor recurrence." (PMID 24244607, 2013). "Furthermore, we demonstrated that Lin28b expressing cells were more responsive to IGF stimulation under serum-free conditions, strongly implicating a role for Lin28b in enhancing tumour survival under stress conditions." (PMID 23482325, 2012). "Previous studies have reported significant association between Lin28b expression and advanced tumor stage; however, none of these studies examined the role of Lin28b in HNSCC." (PMID 23482325, 2012).
tumor (continued). "Stable transfection of the FaDu HNSCC tumor cell line (which has low endogenous Lin28b expression) with this plasmid led to a significant increase in Lin28b expression at both the mRNA and protein levels in two selected stable clones (A1 and D1), compared to GFP-transfected control cells." (PMID 23482325, 2012). "Additionally, our study unravelled a novel molecular mechanism by which Lin28b promoted tumor survival under stress conditions through a let-7-IGF-dependent mechanism." (PMID 23482325, 2012). "Lin28B inhibited accumulation of mature let-7, which resulted in the increased expression of Sox2, Nanog and Oct4, leading to increased self-renewal and tumor growth." (PMID 20805998, 2010). "Additionally, other findings suggest that besides being associated with cellular senescence, the AURKA gene can drive tumor progression through the LIN28B-RAN-AURKA signaling pathway, and it also plays a role in maintaining N-MYC stability in MYCN-amplified NB." (PMID 39135779, 2024). "Importantly, we found that LINC01605 promotes PDAC progression through mTOR signaling pathway activation, which further regulates cholesterol metabolism and thus leads to PDAC tumor growth and liver metastasis; we also found that it may interact with LIN28B." (PMID 39048994, 2024). "Therefore, we tested Fzd4’s level and found that Lin28b could only be detected in both Wnt5a and Fzd4 high-‍expressed tumor cells lines, indicating that intact Wnt5a-Fzd4 pathway is essential for activation of Lin28b in PDAC." (PMID 37898598, 2023). "The hypothesized pro-tumor roles of AVIL specifically through the FOXM1/LIN28B axis is seen in." (PMID 34948433, 2021). "Furthermore, it has been demonstrated that the tumor suppressor miR-26a-5p directly targets LIN28B and AURKA in HB cells, which highlights the relevance of the LIN28B-RAN-AURKA axis in the pathogenesis of this disease and the role of miR-26a-5p as a repressor of this signaling." (PMID 30909459, 2019). "Therefore, modulation of LIN28B by miR-203 may explain, at least in part, why the downregulation of miR-203 during lung tumorigenesis can promote tumor growth." (PMID 28218277, 2017). "For example, the tumor-driving H3.3K27M mutation in pediatric diffuse intrinsic pontine gliomas (DIPGs) results in the inactivation of the PRC2 complex, causing ectopic expression of LIN28B, PLAG1, and PLAGL1, and leading to the de-differentiation and hyperproliferation of tumor cells." (PMID 27588417, 2016). "Thus, strong TRIM71 activity potentially suppresses cellular transformation driven by Lin28B-let-7 in tumors in which this pathway is conserved by attenuating Lin28B protein function, thereby inhibiting tumor cell growth through inhibition of potential let-7 target oncogenes, especially HMGA2." (PMID 27821801, 2016). "Based on our results, we hypothesize that Lin28B inhibits the tumor suppressor activity of miR-212 in AIPC, potentially playing a role in prostate carcinogenesis or progression, while in normal prostate miR-212 suppresses the expression of Lin28B by targeting it mRNA." (PMID 25201220, 2014). "Importantly, LIN28B expression could predict the recurrence of TNM grade II/III tumours after surgical resection." (PMID 25360631, 2014). "Furthermore, our data have unravelled yet another mechanisms by which Lin28b could promote tumour progression, namely through activation of the IGF pro-survival pathway." (PMID 23482325, 2012). "Moreover, the expression of Lin28B significantly correlated with tumour depth (P=0.005)." (PMID 22433967, 2012). "Moreover, knock-down of Lin28B markedly increased let-7 expression, suggesting that miR-200 and let-7 could act as a target for the prevention of tumor recurrence and metastasis in PCa." (PMID 20805998, 2010). "Compact tumor organoids exhibited a higher expression of genes involved in WNT-mediated maintenance of nephron progenitors (e.g. LGR5, MYCN, HMGA2, LIN28B, NCAM, WNT4, BMP7)." (PMID 39740515, 2025).
tumor (continued). "Our study confirms that LIN28B facilitates EC progression through the upregulation of MYC and mediates immunosuppressive tumor microenvironment reprogramming." (PMID 40740861, 2025). "Studies suggest that LIN28B promotes cell survival and tumorigenesis by increasing BCL-2 expression and inhibiting apoptosis, indicating a potential influence on the tumor microenvironment (TME)." (PMID 40746360, 2025). "Together, these data confirm the ability of SOX6 to repress LIN28B and the pro-proliferative genes downstream to the LIN28/Let-7 axis, pointing to a wide tumor suppressor role of SOX6." (PMID 38704454, 2024). "LIN28B, central to an RNP regulon that increases translation of RBPs, is important for tumor initiation in the liver." (PMID 38875287, 2024). "repressing IGF2BP3/c‐MYC/LOC101929709/LIN28B/PI3K–AKT pathway inhibited the Warburg effect and tumor progression." (PMID 38721006, 2024). "Stable LIN28B downregulation resulted in a significant decrease in the tumor markers SOX2, NESTIN, and SOX9 and an increase in the neural differentiation marker GAP43, consistent with the critical role of LIN28B in maintaining stemness." (PMID 38732012, 2024). "Lin28b can be expressed in a variety of CAFs including aSMA+ myofibroblasts and FAP+ myofibroblasts which support tumor growth." (PMID 37898598, 2023). "Lin28B knockout by CRISPR not only suppressed the CSC phenotypes of the NEPC cells but also prevented NEPC xenograft formation and tumor growth." (PMID 36428779, 2022). "By taking the intersection of the two cohorts, we identified 26 upregulated TFs with twofold upregulation in tumour tissues compared with NT liver tissues, although four of them (E2F1, FOXM1, LIN28B, and MYCN) were excluded for overrepresentation." (PMID 36008383, 2022). "In multiple myeloma, the LIN28B/let-7 axis modulates the expression of MYC, which in turn is a let-7 target, suggesting a novel mechanism for therapeutic targeting of the tumor." (PMID 34439740, 2021). "As let-7 target c-MYC and MYCN and LIN28B is a transcriptional target of both c-MYC in multiple human and mouse tumor models and MYCN in NB, the inhibition of let-7 is c-MYC/MYCN-mediated via LIN28." (PMID 34771690, 2021). "This was supported by another research, where low Lin28B expression (from let-7a – Lin28B – IGF-II axis) correlated with the less aggressive OC, lower tumour malignancy and better chemotherapy response." (PMID 34267805, 2021). "Intriguingly, IGF2BP1, LIN28B, and HMGA2 form a self-promoting network antagonizing the tumor-suppressive actions of the let-7 miRNA family." (PMID 32545414, 2020). "To confirm increased stem cell gene expression in these hyperplastic regions, we also assessed the mRNA level of Lin28B, CD34, Lgr6, and Sox2, which can serve as markers for stem-like tumor cells in skin squamous cell carcinoma." (PMID 32895364, 2020). "For example, LIN28B regulates let-7 miRNA, CMTM7 is potential tumor suppressor, possibly silenced by promoter methylation), and ARGHDIB, a regulator of Rho family signaling, can be upregulated in tumors." (PMID 33266012, 2020). "RNAi mediated knockdown of LIN28B decreased proliferation of HCC cells and reduced tumor growth in vivo." (PMID 31906510, 2020). "Our results showed that Lin28B expression in Hep3B/TAX cells and xenograft tumor tissue was significantly decreased in a dose-dependent manner following co-treatment with curcumin and paclitaxel." (PMID 31762817, 2019). "Comparative analyses consistently showed that Lin28B expression was differentially elevated in 8 human PDAC samples and their matched adjacent non-tumor tissues." (PMID 28947981, 2017). "Overexpression of Lin28B alone significantly enhanced tumor formation, whereas co-expression of Lin28B and TRIM71 markedly inhibited tumor growth." (PMID 27821801, 2016). "Three human target genes of anti-Let-7 (HMGA2, LIN28B, and IGFBP2) were upregulated in both the tumor core and peripheral tumor region after ITu injection only." (PMID 27102443, 2016).
tumor (continued). "Taken together, these data indicate that TRIM71 acts through post-transcriptional repression of Lin28B and subsequent modulation of let-7-HMGA2 signaling during tumorigenesis to potentially function as a tumor suppressor." (PMID 27821801, 2016). "The RNA-binding protein Lin28B, an important substrate of TRIM71-mediated ubiquitination, negatively regulates the biogenesis of the tumor-suppressive let-7 family at the post-transcriptional level." (PMID 27821801, 2016). "For example, Wu and his colleague reported that LIN28 and LIN28B expression levels were both increased in 72 primary OSCC and positively correlated with gender, tumor differentiation and patients’ survival." (PMID 26478718, 2015). "Interestingly, LIN28B and its upstream regulator c-Myc are also targets of let-7; consequently, a c-Myc-LIN28B-let-7 axis, or feedback loop, which may serve to repress tumour growth, may exist." (PMID 25360631, 2014). "Additionally, LIN28B contributes to CRC tumor growth through the LIN28B/IRS1 axis, a target of miR-30a-5p, which promotes tumor proliferation." (PMID 40746360, 2025). "This study specifically investigates whether LIN28B promotes EC progression through MYC upregulation and its influence on tumor immune microenvironment remodeling." (PMID 40740861, 2025). "The development of small molecule inhibitors or antagonists targeting molecules like ENO1, LIN28b, UCA1, and NEAT1 may be effective in inhibiting tumor growth and metastasis." (PMID 40384875, 2025). "Further experiments to investigate whether EGCG can also affect LIN28B pro-tumorigenic activity in a let-7-independent manner are definitely needed and may strengthen the relevance of EGCG in NB and potentially other tumor types." (PMID 38732012, 2024). "Even if the mechanisms by which LIN28B drives tumor development and progression are not completely understood, it is well-known that LIN28B acts as a negative regulator of the biogenesis of the tumor suppressors let-7 miRNAs." (PMID 38732012, 2024). "The second major observation is that continuous overexpression of LIN28B did not lead to more aggressive tumor progression compared with the other 2 models, suggesting the lack of a maintenance requirement for LIN28B." (PMID 38875287, 2024). "Here, we showed that the lack of LIN28A and LIN28B had no impact on liver development or function, but largely abrogated tumor initiation driven by powerful oncogenes such as NRAS, CTNNB1, YAP, and AKT." (PMID 38875287, 2024). "Together, these data indicate that LIN28B is not required for tumor maintenance in some HCCs exhibiting LIN28B overexpression." (PMID 38875287, 2024). "In their study, overexpression of Lin28b alone was not sufficient for tumor formation in Math1‐positive cerebellar granular neuron precursors or Nestin‐positive neuronal precursor cells." (PMID 37341142, 2023). "Knocking-out Wnt5a but not Wnt10a in tumors suppressed the ability of tumor cells to induce Lin28b expression in CAFs, highlighting the role of Wnt5a in Lin28b induction." (PMID 37898598, 2023). "We analyzed tumor sections from patients with MYC amplified Group 3 MB as well as a patient‐derived orthotopic xenograft (PDOX) utilizing the BT52CTC patient cells and confirmed expression of LIN28B in these tumors." (PMID 37341142, 2023). "In the animals that had to be euthanized due to tumor burden, we observed that the LIN28B knockdown tumors re‐expressed or overexpressed LIN28B rather than using an alternate pathway to drive tumor growth." (PMID 37341142, 2023). "The MMTV-Neu mouse model (HER2+ subtype) also demonstrated that Lin28B expression did not accelerate tumor growth at the initial sites, but increased the incidence of lung metastasis." (PMID 35173168, 2022). "Interestingly, the LIN28B/MYC/miR-34a-5p pathway can be therapeutically exploited: in fact, when using LIN28B inhibitors, miR-34a-5p increases and PKM2 decreases while tumor growth and lung metastasis are suppressed." (PMID 35348905, 2022).